SLC6A6 (solute carrier family 6 member 6)
Description:
Mediates sodium- and chloride-dependent transport of taurine, a key amino acid. Taurine acts as an anti-aging agent by reducing cellular senescence and combating oxidative stress: levels decline with age and supplementation has been shown to extend lifespan (By similarity). In addition to mediate extracellular taurine uptake, also able to mediate transport of taurine into mitochondria, sustaining mitochondrial translation. Can also mediate transport of beta-alanine, hypotaurine and gamma-aminobutyric acid (GABA).
Synonyms: TauT; HTRDC
Tractability: Small molecule: a structure with a bound ligand is known; it belongs to a druggable protein family. Antibody: UniProt places it where antibodies can reach, with high confidence; its Gene Ontology location is reachable by antibodies, with high confidence; UniProt predicts a signal peptide or a membrane-spanning region. PROTAC: ubiquitination databases record sites on it; its protein half-life has been measured; a small molecule that binds it is known.
Target class: SLC superfamily of solute carriers; SLC06 neurotransmitter transporter family; Electrochemical transporter; Transporter
Gene: Protein-coding gene on chromosome 3 (14,402,565 to 14,489,349, forward strand). Ensembl gene ENSG00000131389.
Subcellular location: Cell membrane; Mitochondrion inner membrane
Subcellular location (Human Protein Atlas): Cell Junctions; Cytosol
Pathways (Reactome):
Transport of small molecules: Amino acid transport across the plasma membrane
Gene Ontology:
Molecular function: alanine transmembrane transporter activity; amino acid transmembrane transporter activity; amino acid:sodium symporter activity; beta-alanine transmembrane transporter activity; gamma-aminobutyric acid transmembrane transporter activity; taurine:sodium symporter activity; gamma-aminobutyric acid:sodium:chloride symporter activity
Biological process: alanine transport; amino acid import across plasma membrane; positive regulation of cell differentiation; positive regulation of mitochondrial translation; taurine transmembrane transport; amino acid transport; gamma-aminobutyric acid import; import across plasma membrane; negative regulation of cellular senescence; sodium ion transmembrane transport; transport across blood-brain barrier; beta-alanine transport; modulation of chemical synaptic transmission; neurotransmitter transport
Cellular component: apical plasma membrane; basolateral plasma membrane; microvillus membrane; mitochondrial inner membrane; plasma membrane; dendrite; membrane; neuronal cell body; GABA-ergic synapse; postsynaptic membrane
Genetic constraint (gnomAD): Loss-of-function variants: 15 observed, 57.91 expected, observed/expected ratio (o/e) 0.26, 90% interval 0.17 to 0.4. The upper end of that interval is the gene's LOEUF score, 0.4, which puts it in group 1 of 6, group 1 being the genes least tolerant of losing a copy. Missense variants: 402 observed, 723.71 expected, observed/expected ratio (o/e) 0.56, 90% interval 0.51 to 0.6. Synonymous variants: 280 observed, 294.67 expected, observed/expected ratio (o/e) 0.95, 90% interval 0.86 to 1.05.
Gene-disease validity (ClinGen):
ClinGen rates the evidence that SLC6A6 causes each of these diseases.
hypotaurinemic retinal degeneration and cardiomyopathy (autosomal recessive): Limited.
Homologues: Orthologues: chimpanzee SLC6A6 (99% identical), macaque SLC6A6 (99% identical), rabbit SLC6A6 (96% identical), dog SLC6A6 (95% identical), rat Slc6a6 (94% identical), mouse Slc6a6 (93% identical), pig SLC6A6 (92% identical), guinea pig SLC6A6 (92% identical), tropical clawed frog slc6a6 (82% identical), zebrafish slc6a6a (79% identical), zebrafish slc6a6b (76% identical). Paralogues in human: SLC6A11 (59% identical), SLC6A13 (59% identical), SLC6A12 (58% identical), SLC6A8 (54% identical), SLC6A2 (42% identical), SLC6A5 (41% identical), SLC6A7 (41% identical), SLC6A3 (41% identical), SLC6A14 (40% identical), SLC6A4 (40% identical), SLC6A9 (39% identical), and 6 more.
Diseases named in the same sentence as SLC6A6 in open-access papers:
SLC6A6 is named in the same sentence as 99 diseases in open-access papers, as found by Europe PMC text mining. Sharing a sentence is not in itself a finding about the gene and the disease. The quoted sentences say what the papers report.
retinal degeneration (13 papers, 2005 to 2026). Degeneration of the retina. "Do newly identified biallelic SLC6A6 variants confirm its involvement in retinal degeneration and expand the genetic and clinical spectrum of the disease?" (PMID 41343195, 2026). "Complementary to these preclinical studies, compassionate-use taurine supplementation in siblings with SLC6A6 variants (encoding the taurine transporter) demonstrated reversal of cardiomyopathy and arrest of retinal degeneration." (PMID 41522673, 2026). "Another candidate gene, the taurine transporter SLC6A6, has been linked to early retinal degeneration." (PMID 40495383, 2025). "SLC6A6 mutations in the taurine biosynthesis gene cause cardiomyopathy, and more specifically to the eye, retinal degeneration." (PMID 40943474, 2025). "Of note, severe retinal degeneration was observed in mice mutated in SLC6A6, a gene encoding a transporter of the amino acid taurine." (PMID 16168081, 2005). "However, in ocular studies, one previous study found that biallelic mutation of human SLC6A6 could cause early retinal degeneration." (PMID 33946922, 2021). "A recent study on a consanguineous family reported that a biallelic mutation of human SLC6A6, which encodes the TAUT, is linked to early-onset pan-retinal degeneration." (PMID 31878022, 2019).
cardiomyopathy (11 papers, 2010 to 2026). A disease of the heart muscle or myocardium proper. "SLC6A6 is a metabolism-related gene, and SLC6A6 knockout mice exhibit a cardiomyopathy with myocardial atrophy phenotype, which also provides a potential mechanism for TIC." (PMID 35097033, 2021). "In addition, children with a defective taurine transporter gene (SLC6A6) experience taurine deficiency, and develop retinopathy and cardiomyopathy similar to that noted in feline and canine studies." (PMID 32957558, 2020).
Obesity (7 papers, 2015 to 2025). Accumulation of substantial excess body fat. "Slc6a6 knock out mouse models demonstrate a phenotype of dilated cardiomyopathy with cardiac atrophy, lower fasting blood glucose, acceleration of glycolysis in skeletal muscle and susceptibility to development of obesity when placed on a high fat diet." (PMID 28101782, 2017). "In the present review, we highlight the unusual involvement of selective amino acid transporters in macropinocytosis (SLC38A5/SLC38A3) and diet-induced obesity/metabolic syndrome (SLC6A19/SLC6A14/SLC6A6)." (PMID 35204736, 2022). "Unfortunately, this also applies to the role of taurine and its transporter SLC6A6 in obesity." (PMID 35204736, 2022). "Furthermore, SLC6A6-null mice are lean and show resistance to diet-induced obesity." (PMID 35204736, 2022).
gastric cancer (5 papers, 2021 to 2025). A primary or metastatic malignant neoplasm involving the stomach. "Overexpression of SLC6A6 was found also in gastric cancer, which was connected with poor prognosis, advanced tumour stage, and aggressiveness of cancer." (PMID 36835201, 2023). "Studies reported that upregulated SLC6A6 induces tumorigenesis and reduces clinical outcomes in gastric cancer." (PMID 34336645, 2021).
diabetes (4 papers, 2015 to 2025). "We have shown that alteration of the TauT gene (also known as SLC6A6) has a substantial effect on the susceptibility to development of extensive diabetic kidney disease in both TauT+/- and TauT-/-mouse models of diabetes." (PMID 25629817, 2015). "Additionally, the mechanism by which SLC6A6 expression changes differently in β‐cells during aging and diabetes remains unclear." (PMID 40458841, 2025).
heart failure (4 papers, 2017 to 2024). Inability of the heart to pump blood at an adequate rate to meet tissue metabolic requirements. "Solute carrier family 6, member 6 (SLC6A6), is a transporter of taurine, an endogenous sulfur-containing beta-amino acid, associated with calcium handling, protection against ischemia–reperfusion injury, heart failure ischemic heart disease, and diabetic cardiomyopathy." (PMID 28101782, 2017). "SLC6A6 is implemented in calcium handling and in protection against ischemia–reperfusion injury, heart failure ischemic heart disease, and diabetic cardiomyopathy." (PMID 35413811, 2022).
cervical cancer (3 papers, 2017 to 2025). A primary or metastatic malignant neoplasm involving the cervix. "Modulates invasion, migration, apoptosis, and proliferation of cervical cancer cells, negatively downregulates SLC6A6, downregulation of miRNA increase SLC6A6 expression, miRNA inhibits cervical cancer tumorigenesis, downregulation promotes cervical cancer pathogenesis." (PMID 39185567, 2025). "Meanwhile, the tumor-suppressor effect of miR-3156-3p may be due to the regulation of SLC6A6 in cervical cancer." (PMID 28160779, 2017).
colon cancer (3 papers, 2021 to 2025). "In the colon tumors, MEBOCOST analysis revealed that GABA mediated the mCCC between colon cancer and NK cells through two sensors, namely, SLC6A6 and GABRG2." (PMID 40568942, 2025). "In addition, knockdown of either PIK3CA or SLC6A6 resulted in decreased expression of α-SMA and increased expression of E-cadherin along with decreases in CD44, CD133, and Nanog, indicating a loss in markers for EMT and colon cancer stem cells." (PMID 34571860, 2021). "Given that oxaliplatin is also a standard chemotherapeutic agent used in colon cancer treatment, we also examined the expression of molecular signature genes PIK3CA, SLC6A6, ASAP-1 and TMEM-43 in colon cancer cells resistant to this drug." (PMID 34571860, 2021). "To test whether PIK3CA, SLC6A6, TMEM-43, and ASAP-1 expression is driven by CLDN1 and CLDN7 expression, we analyzed these genes and proteins in CLDN1-overexpressing SW480 (SW480CLDN1) and CLDN7-knockdown DLD-1 (DLDCLDN7KD) colon cancer cell lines." (PMID 34571860, 2021).
colorectal cancer (3 papers, 2017 to 2023). A primary or metastatic malignant neoplasm that affects the colon or rectum. "It has been reported that SLC6A6 promotes the survival and multidrug resistance of colorectal cancer." (PMID 33519944, 2021). "A recent study found that SLC6A6 plays an important role in the maintenance of side population cells and their cancer stem cell properties, including enhanced prosurvival activity, tumor initiation and chemoresistance in colorectal cancer." (PMID 28160779, 2017). "Additionally, the expression of colorectal cancer markers was decreased in SLC6A6-KD lines." (PMID 36835201, 2023).
Hepatitis (3 papers, 2012 to 2022). Inflammation of the liver. "For the hepatitis network, important identified pathways were, again, mainly involved in responses to increased oxidative stress, which initiates cytoprotective action of upregulated HMOX1 leading to mitochondrial dysfunction associated with downregulation of the SLC6A6 taurine transporter." (PMID 35865277, 2022).
leukemia (3 papers, 2025 to 2026). A malignant (clonal) hematologic disorder, involving hematopoietic stem cells and characterized by the presence of primitive or atypical myeloid or lymphoid cells in the bone marrow and the blood. "Of these signals, TAUT, encoded by SLC6A6, was strongly associated with poor prognosis in human leukaemias and emerged as a key regulator of AML." (PMID 40369079, 2025). "Our prior work has identified a key role of taurine produced by bone marrow osteolineage cells in supporting the growth of taurine transporter (TauT or Slc6a6) expressing leukemia cells." (PMID 41507125, 2026). "A recent study demonstrated that bone marrow stromal cells actively support leukemogenesis by supplying taurine to leukemia stem cells via the taurine transporter SLC6A6 (TAUT)." (PMID 41003014, 2025). "Our analyses of available gene expression datasets indicate that SLC6A6 expression is enriched in leukaemia stem/progenitors as compared to more mature blasts." (PMID 40369079, 2025). "In addition, Slc6a6 expression in MSCs decreases during leukemia progression." (PMID 41507125, 2026). "As SLC6A6 expression was significantly enriched in both human bcCML and AML LSCs as compared to the controls, we focused our studies on SLC6A6, as it may be broadly required for growth of aggressive leukaemias." (PMID 40369079, 2025).
pancreatic cancer (3 papers, 2022 to 2025). "The overexpression of SLC6A6 in pancreatic cancer is determined in multiple gene expression-based studies." (PMID 35359382, 2022). "We identified 7 highly expressed pancreatic cancer cell surface receptors (MET, NPR3, IL1RAP, SLC2A1, SLC6A6, GABRP, and TMPRSS4) in all the analyzed datasets." (PMID 35359382, 2022). "Overexpressed pancreatic cancer receptors include SLC2A1, MET, IL1RAP, NPR3, GABRP, SLC6A6, and TMPRSS4." (PMID 35359382, 2022). "The L5 proteins of 3 serotypes of adenovirus HAdV2, HAdV3, and HAdV5 are docked with the seven highly expressed pancreatic cancer receptors SLC2A1, MET, IL1RAP, NPR3, GABRP, SLC6A6, and TMPRSS4." (PMID 35359382, 2022). "However, knockdown of SLC6A6 and SLC6A8 did not diminish the promoting effect of GAA on pancreatic cancer cell migration, possibly because these cells have a greater dependence on passive diffusion of extracellular GAA or de novo GAA synthesis than on the expression of SLC6A6 and SLC6A8." (PMID 37370109, 2023).
type 2 diabetes (3 papers, 2016 to 2025). "We used the Accelerating Medicines Partnership Type 2 Diabetes Knowledge Portal to understand the effect of missense mutations in genes encoding the hepatic GABA transporters (SLC6A6, SLC6A8, SLC6A12, and SLC6A13)." (PMID 34192533, 2021). "Interestingly, when comparing islets from healthy elderly individuals to those with type 2 diabetes (HbA1c ≥ 6.5%), SLC6A6 was significantly downregulated in diabetic conditions, while the taurine biosynthesis genes remained unchanged." (PMID 40458841, 2025).
atherosclerosis (2 papers, 2023 to 2025). A disease characterized by the build-up of fatty material and calcium deposition in the arterial wall resulting in partial or complete occlusion of the arterial lumen. "Several studies have reported that oxidative stress and reactive oxygen species (ROS) downregulate SLC6A6, while ROS levels are increased in atherosclerosis, vascular injury, and VSMCs treated with PDGF-BB." (PMID 36769341, 2023). "Moreover, SLC6A6 overexpression further prevents vascular stenosis and atherosclerosis formation by inhibiting VSMC proliferation, dedifferentiation, and migration." (PMID 41393259, 2025). "Therefore, we propose that SLC6A6 may be a promising target for decreasing neointimal formation in atherosclerosis patients." (PMID 36769341, 2023). "To translate our findings from rats to humans, we examined the expression of SLC6A6 in human femoral arteries from patients with or without atherosclerosis." (PMID 36769341, 2023). "In this study, tissue immunofluorescence demonstrated that SLC6A6 expression is localized to the medial layer and adventitia of the normal vasculature, while almost not in the neointimal layer after vascular injury and atherosclerosis." (PMID 36769341, 2023). "In this study, mRNA and protein levels of SLC6A6 were examined using models of VSMC phenotype switching in vivo and in vitro and human artery samples with or without atherosclerosis." (PMID 36769341, 2023).
Blindness (2 papers, 2011 to 2012). Blindness is the condition of lacking visual perception defined as a profound reduction in visual perception. "Taurine transporter knockout mice (slc6a6-/- or Taut-/- mice) exhibit decreased taurine levels in many tissues and an age-dependent degeneration of photoreceptor cells by apoptosis leading to blindness at an early age." (PMID 22174898, 2011).
chronic kidney disease (2 papers, 2015 to 2024). Impairment of the renal function secondary to chronic kidney damage persisting for three or more months. "Furthermore, genes that have been implicated in chronic kidney disease (CKD), such as Slc6a6 were up-regulated in ECs, and Umod, Cacna1d, Ddx1 were specifically up-regulated in PTs." (PMID 38641839, 2024).
dilated cardiomyopathy (2 papers, 2017 to 2023). Cardiomyopathy which is characterized by dilation and contractile dysfunction of the left and right ventricles. "Taken together, our findings of trastuzumab induced down-regulation of SLC6A6 in human iPSC-derived cardiomyocytes, and the reported phenotypes of dilated cardiomyopathy and altered metabolism in Slc6a6 knock-out mice provide a potential mechanism towards trastuzumab related cardiotoxicity." (PMID 28101782, 2017).
Duchenne muscular dystrophy (2 papers, 2018 to 2025). Duchenne muscular dystrophy (DMD) is a neuromuscular disease characterized by rapidly progressive muscle weakness and wasting due to degeneration of skeletal, smooth and cardiac muscle. "In the murine Duchenne muscular dystrophy model, taurine content of muscle was low, mostly early in disease progression, and a reduction of its transporter SLC6A6 was observed." (PMID 30364257, 2018).
myocardial ischemia (2 papers, 2015 to 2024). A disorder of cardiac function caused by insufficient blood flow to the muscle tissue of the heart. "Genes like NRM, SLC6A6, and PTPRE are involved in Rheumatoid Arthritis, Myocardial Ischemia and Asthma diseases in humans." (PMID 38674383, 2024).
adenovirus infection (1 paper, 2023). "SLC6A6 gain- and loss-of-function approaches were performed by adenovirus infection or small interfering RNA (siRNA) transfection, respectively." (PMID 36769341, 2023).
bovine tuberculosis (1 paper, 2025). "Likewise, a polymorphism in SLC11A1 was associated to bovine tuberculosis (bTB) resistance while SLC6A6 was suggested to be associated with bTB resistance in Irish Holsteins." (PMID 40660125, 2025).